TTN (titin)
Diseases named in the same sentence as TTN in open-access papers (continued):
Sharing a sentence is not in itself a finding about the gene and the disease.
tumor (continued). "Mutations in MUC16 and TTN were associated with associated with improved overall survival (OS), and the mutation status and number of mutations in MUC16 and TTN were effective predictors of tumor mutational burden (TMB)." (PMID 40567896, 2025). "Additionally, we investigate how TTN mutations, by altering the TIME, impact the infiltration of CD4 and CD8 T cells, thereby enhancing the activation of anti‐tumour immunity within the body." (PMID 39748197, 2025). "Given that MDSCs induced by the DLL4-MCT4 axis can promote tumor immune evasion in TNBC with TTN inactivation, we wondered whether blocking the DLL4-MCT4 axis could inhibit tumor growth." (PMID 41326912, 2025). "For example, TTN and ANKRD36, both highly mutated in deceased patients and listed among the top-ranked genes, are associated with cytoskeletal reorganization and structural maintenance, critical processes for tumor invasion and metastasis." (PMID 40722723, 2025). "Furthermore, p300 and key stemness-related factors were upregulated and p300 was essential for tumor stemness in the TTN-Mut group in both PDO1 and PDO2." (PMID 41326912, 2025). "Results revealed that in both the CT26 model in BALB/c mice and the immunocompetent C57BL/6 mouse model with MC38 cells, tumours with TTN‐KO exhibited decreased growth rates compared with the WT group, which further decreased in growth rate when combined with radiotherapy." (PMID 39748197, 2025). "As shown in the waterfall plot, there are variations in the tumor mutational burden (TMB) of two subtypes, and the frequencies of TTN, CSMD3, MUC16, RYR2, LRB1P and ZFHX4 mutations in the high-risk group were considerably higher than those in the low-risk group." (PMID 38345559, 2024). "It should also be noted that titin is constitutively expressed by human lymphocytes, and therefore, abnormal titin expression appears to be involved in the induction and progression of the tumor process." (PMID 38275878, 2024). "Also of note is the fact that titin plays an important role in the influx of T lymphocytes into inflamed tissues, including the tumor microenvironment." (PMID 38275878, 2024). "Based on the conducted statistical analysis we have shown, there was a statistically significant decrease in the expression of irisin, ghrelin, and titin in the cancerous tissue in comparison with healthy tissue from the tumor margin (t-Student test; p < 0.05)." (PMID 38275878, 2024). "Changes in TTN expression or alterations in its interaction with signaling molecules could potentially impact cellular signaling events within the tumor microenvironment." (PMID 37671167, 2023). "In these tumor samples, the top 10 mutated genes included PIK3CA, MUC4, and TTN." (PMID 35528180, 2022). "Finally, although the mutations in TTN and MUC16 appeared to be relatively common (24% and 10%), these two genes have rarely been recognized as tumor-associated genes." (PMID 35359413, 2022). "Further investigations are needed to explore whether TTN plays roles in sex-specific chromatin regulation and/or solid stress derived from tumor growth." (PMID 36118521, 2022). "In fact, both TTN and MUC17 have been directly or indirectly recognized as tumor-associated genes." (PMID 32731431, 2020).
tumor (continued). "TTN, as the biggest known protein, may affect multiple aspects of tumor biology." (PMID 41326912, 2025). "Additionally, TTN mutations may promote the infiltration of CD4 and CD8 T cells, altering the TIME and boosting anti‐tumour immune activation." (PMID 39748197, 2025). "The precise role of TTN in tumor immune microenvironment is not clear, and the animal model is still needed to elucidate the underlying mechanism that how TTN promotes evolution and dissemination of tumors through mediating tumor-infiltrating immune cells." (PMID 35875159, 2022). "Interestingly, TTN, PIK3CA, MUC4, KMT2C, and MUC16 were the top mutations in both cohorts, which were reported to regulate various tumor biological processes in CC, indicating that they are less participated in the process of immune infiltration but mainly involved in tumorigenesis and progression." (PMID 33553190, 2021). "We cocultured MDSCs with 4T1-TTN-WT, 4T1-TTN-KO, and 4T1-TTN-KO-DLL4-KO cells, respectively, to investigate the mechanism of MDSCs suppressed T cell-mediated anti-tumor immunity in TTN-inactivated tumors." (PMID 41326912, 2025). "Subsequently, equal amounts of WT or TTN‐KO cells were subcutaneously inoculated into BALB/c or C57BL/6 mice, and tumour growth was monitored." (PMID 39748197, 2025). "The TITIN (TTN) gene has not been extensively explored as a tumor-related gene in the literature, although it ranks eighth on our list." (PMID 37313463, 2023). "Although not previously related specifically to DGC, TTN was found as one of the top five hub genes of a specific co‐expression module positively correlated with GC pathological tumour and lymph node stages." (PMID 33724653, 2021).
tumor (continued). "Furthermore, blockade of the DLL4 signaling may sensitize tumor cells to chemotherapy and immunotherapy in TNBC with TTN inactivation." (PMID 41326912, 2025). "Moreover, off-target toxicities, such as nonspecific recognition by the TCR, lead to off-target/off-tumor toxicities, such as a MAGE-A3-specific transgenic TCR recognizing the Titin protein and causing cardiac death." (PMID 37173386, 2023). "In addition, unlike DMD and LAMA2 which were deleted, only missense mutations were seen in TTN, as has been reported in a number of other tumor types and is not unexpected given the large size of the TTN gene." (PMID 30575736, 2018).
myopathy (53 papers, 2007 to 2025). A disease of the muscle in which the muscle fibers do not function properly. "This study expands the spectrum of TTN‐related myopathies, emphasizing exon 363's pathogenic significance." (PMID 41246854, 2025). "Titinopathies are a group of myopathies caused by defects in the titin gene (TTN—OMIM-188840) localized on chromosome 2q31.2." (PMID 39684706, 2024). "Five synonymous NEB, RYR1, and TTN variants were found to impact on splicing in three families with NM, one family with core myopathy and one family with CNM, respectively." (PMID 38982518, 2024). "The inheritance pattern of titin variants linked to early onset myopathy is typically compound heterozygous, where one variant is inherited from the mother and a second variant, also in titin, is inherited from the father." (PMID 37549721, 2023). "The mutations of TTN have been linked to a wide range of dominantly and recessively inherited myopathies." (PMID 36675693, 2022). "Herein, we report two zebrafish models, which carry titin mutation linked to a cardiac (Pickwickm171) and a skeletal (runzel) myopathy, and the medaka cardiac model nsh." (PMID 36065969, 2022). "In the last few years, an increasing number of inherited myopathies and cardiac disorders associated with titin (TTN) variants have been identified." (PMID 36065969, 2022). "A major emphasis of our study was the detailed functional and biophysical characterization of the TTN missense variants identified in our cohort, a particular diagnostic challenge in the ascertainment of TTN-related myopathies." (PMID 33449170, 2021). "Mutations in the sarcomeric protein titin, encoded by TTN, are emerging as a common cause of myopathies." (PMID 33449170, 2021). "Here, we present a combined clinico-pathological, genetic and biophysical approach to the diagnosis of TTN-related myopathies and the pathogenicity ascertainment of TTN missense variants." (PMID 33449170, 2021). "Mechanical measurements on skinned human myofibers incubated with exogenous small HSPs suggested that the elevated PT seen in myopathy is caused, in part, by chaperone-binding to the titin springs." (PMID 28915917, 2017). "Interestingly, all of these genes are associated with genetic (cardio)myopathies in humans (TTN, NEB, MYBPC1, TNNT3 and TPM1) or mice (PDLIM3)." (PMID 37000196, 2023). "Patients with TTN variants showed wide-ranging clinical presentations, from congenital-onset arthrogryposis multiplex congenita to late-onset axial muscle weakness with minicore myopathy." (PMID 35628876, 2022). "Here, titin is inactivated in adult mouse muscles, which causes sarcomere disassembly, protein mis-expression and force impairment, recapitulating key alterations in critical illness myopathy patient muscles." (PMID 32900999, 2020). "Here, we fully characterized, using an integrated approach (deep phenotyping, muscle morphology, mRNA and protein evaluation in muscle biopsies), two siblings with congenital multicore myopathy harboring three TTN variants predicted to affect titin stability and titin‐myosin interactions." (PMID 32307885, 2020). "Thus, they suggested that titin loss is a contributing factor to critical illness myopathy." (PMID 33561946, 2021). "In contrast, over half of the patients with ICI‐related myopathy are positive for anti‐striational antibodies (anti‐titin and anti‐Kv1.4 antibodies)." (PMID 38962456, 2024). "Although the role of titin in muscle elasticity is well established, the specific impact of mutations in MTT-only exons on early-onset myopathies remains underexplored." (PMID 39684706, 2024). "First, we reported 18 novel variations in 6 myopathy-causing genes, including RYR1, NEB, ACTA1, DNM2, TTN and TNNT1, and we described the clinical discrepancy between our patients and previous reports, especially in RYR1- and TNNT1- related myopathy." (PMID 35081925, 2022).
myopathy (continued). "RYR1 and TTN therefore clearly benefit from high throughput technologies such as NGS and are proving to be a major cause in myopathies." (PMID 32403337, 2020). "Quantitation of the gold particle distribution on immunoelectron micrographs (n = 30 sarcomeres) verified that the vast majority of αB-crystallin (60–70% of gold particles) was in the elastic I-band in myopathy fibers, presumably bound to the titin springs." (PMID 28915917, 2017). "The binding of HSPs to titin suggested a role for these molecular chaperones in the pathomechanism of myopathy subtypes, which are presenting with reduced contractile force generation and increased muscle stiffness." (PMID 28915917, 2017). "Correlative immunofluorescence and immunoelectron microscopy showed that two small HSPs (HSP27 and αB-crystallin) and the ATP-dependent chaperone HSP90 translocated to the titin springs in myopathy." (PMID 28915917, 2017). "We found that, of all HSPs studied, only HSP27, αB-crystallin and HSP90 were translocated from the cytosol or sarcomeric Z-disc in healthy human muscles to the titin springs in myopathy." (PMID 28915917, 2017). "Because titin-dependent PT modulates the active contractile properties of skeletal myofibers, the increased PT observed in human myopathy presumably affects, to some degree, the developed tension of patient muscles." (PMID 28915917, 2017). "In their other study, a titin-inactivated mouse had sarcomere disintegration, myocyte de-stiffening, and force impairment, which were consistent with the muscle damage of critical illness myopathy." (PMID 33561946, 2021). "Moreover, the titin:MHC ratio also remained unaltered in myopathy, suggesting that the increased PT in diseased myofibers was not due to changes in titin expression levels." (PMID 28915917, 2017). "Indeed, alterations in the stiffness of cardiac titin are related to a number of myopathies, such as diastolic dysfunction." (PMID 27546612, 2016). "Our mouse cell transplantation data suggest that in myopathies compartmentalization of the therapeutic protein after fusion of a healthy cell with a diseased fiber might restrict the therapeutic effect (most prominent for the giant protein titin)." (PMID 39688479, 2024). "Indeed, Fc-TWEAK may have affected the expression of the shared aberrantly expressed genes identified with the myogenesis, myopathy, and glucose metabolism PCR arrays such as Pax7 and Titin as well as the pathways (e.g. MAPK and AMPK)." (PMID 35902978, 2022). "In contrast to disease-causing proteins in many other myopathies, the mutant titin protein could not be found in cytoplasmic bodies but in other myofibrillar proteins." (PMID 35846001, 2022). "As TTN variants are not infrequent amongst control populations, information is needed regarding consistent clinico-pathological features that support the diagnosis of a TTN-related myopathy, and how to ascertain pathogenicity confidently, particularly with regards to TTN missense variants." (PMID 33449170, 2021). "All-titin phosphorylation and site-specific phosphorylation in the PEVK region were reduced in myopathy, which would be predicted to lower PT." (PMID 28915917, 2017). "By examining biopsy material from control subjects, 17 patients with different myopathies, and muscle from animal models of hereditary myopathies, we found that massive HSP-binding to titin is a common feature in dystrophic and MFM muscle disorders." (PMID 28915917, 2017). "Structural muscle genes (ACTA1, TTN) were reduced to levels similar to those in DM, while markers of muscle regeneration (NCAM1, PAX7, MYH3, MYH8) were only mildly increased compared to normal muscle, and lower than in other inflammatory myopathies." (PMID 41441888, 2025).
myopathy (continued). "Indeed, 5 out of the top 10 transcripts with the most AS events corresponded to sarcomeric genes, including TTN and NEB, indicating that abnormal nuclear pre-mRNA splicing of functionally important sarcomeric genes could contribute to the pathogenic mechanism of the myopathy in our family." (PMID 37000196, 2023). "In contrast, patients with early-onset MG, those with other myopathies and healthy controls did not have anti-titin or anti-Kv1.4 antibodies with some exceptions, but they possessed anti-ryanodine receptor antibodies." (PMID 30918333, 2019). "Among the myopathies, emerging data suggest a specific role for LCD-containing RBPs such as TDP-43 and hnRNPA2/B1 in regenerating muscle, where they are thought to stabilize large muscle-specific transcripts (e.g., TTN, NEB), aid in their transport, and facilitate pre-mRNA splicing." (PMID 35484142, 2022).